TAS2R8 (taste 2 receptor member 8)
Description:
Receptor that may play a role in the perception of bitterness and is gustducin-linked. May play a role in sensing the chemical composition of the gastrointestinal content. The activity of this receptor may stimulate alpha gustducin, mediate PLC-beta-2 activation and lead to the gating of TRPM5.
Synonyms: T2R8; TRB5
Tractability: Antibody: its Gene Ontology location is reachable by antibodies, with high confidence; UniProt predicts a signal peptide or a membrane-spanning region. PROTAC: a small molecule that binds it is known.
Target class: Membrane receptor; Taste receptor (taste family GPCR); Taste family G protein-coupled receptor
Gene: Protein-coding gene on chromosome 12 (10,806,051 to 10,807,286, reverse strand). Ensembl gene ENSG00000121314.
Subcellular location: Membrane
Pathways (Reactome):
Signal Transduction: Class C/3 (Metabotropic glutamate/pheromone receptors); G alpha (i) signalling events
Sensory Perception: Sensory perception of sweet, bitter, and umami (glutamate) taste
Gene Ontology:
Molecular function: bitter taste receptor activity; protein binding; taste receptor activity; G protein-coupled receptor activity
Biological process: detection of chemical stimulus involved in sensory perception of bitter taste; G protein-coupled receptor signaling pathway; sensory perception of taste
Cellular component: membrane; plasma membrane
Genetic constraint (gnomAD): Missense variants: 394 observed, 369.99 expected, observed/expected ratio (o/e) 1.06, 90% interval 0.98 to 1.16. Synonymous variants: 139 observed, 129.07 expected, observed/expected ratio (o/e) 1.08, 90% interval 0.94 to 1.24.
Homologues: Orthologues: chimpanzee TAS2R8 (99% identical), macaque TAS2R8 (86% identical). Paralogues in human: TAS2R9 (47% identical), TAS2R7 (47% identical), TAS2R3 (39% identical), TAS2R10 (36% identical), TAS2R19 (35% identical), TAS2R46 (35% identical), TAS2R42 (34% identical), TAS2R50 (34% identical), TAS2R30 (33% identical), TAS2R13 (33% identical), TAS2R14 (32% identical), TAS2R20 (32% identical), and 11 more.
Diseases named in the same sentence as TAS2R8 in open-access papers:
TAS2R8 is named in the same sentence as 7 diseases in open-access papers, as found by Europe PMC text mining. Sharing a sentence is not in itself a finding about the gene and the disease. The quoted sentences say what the papers report.
neuroblastoma (6 papers, 2017 to 2024). Neuroblastoma (NB) is the most common solid, extracranial childhood tumor. "In neuroblastoma cells, TAS2R8 and TAS2R10 play an important role in inhibiting the self-renewal potential and the invasion ability of cancer cells." (PMID 32793492, 2020). "Our results are also in agreement with the previously reported role of TAS2R8 and TAS2R10 in abrogating migration of neuroblastoma cells." (PMID 32793492, 2020).
tumor (5 papers, 2017 to 2024). "The upregulation of TAS2R8 and TAS2R10 counteracted gene expression of MMP-2 and P-selectin in tumour tissues, indicating an improved cell adhesion and therefore a reduced metastatic potential." (PMID 34885005, 2021). "Effect of over-expressed TAS2R8 and TAS2R10 on tumor incidence, final tumor volume, and tumor weight." (PMID 28467517, 2017). "Here, stable expressions of TAS2R8 and TAS2R10 suppressed tumor incidence and tended to inhibit tumor growth." (PMID 28467517, 2017).
cancer (2 papers, 2017 to 2024). A tumor composed of atypical neoplastic, often pleomorphic cells that invade other tissues. "In the present study, both TAS2R8 and TAS2810 exhibited anti-cancer stemness and anti-invasion effects." (PMID 28467517, 2017). "In the present study, the role of TAS2R8 and TAS2R10 in the stemness of the NB cancer cells examined suggests their potential as chemotherapeutic targets, despite previously characterizations of TAS2Rs as elusive receptors with distinct signaling pathway and functions compared with other GPCRs." (PMID 28467517, 2017). "The results of the present study demonstrate that TAS2R8 and TAS2R10 are endogenously expressed in NB cancer cells and they play noticeable roles in inhibiting the stemness, migration, and invasion of these cancer cells." (PMID 28467517, 2017).
TAS2R8 also shares sentences with these, for which no sentence is quoted: glioma (2 papers); asthma (1); neurologic disease (1); Parkinson disease (1).